LINC01180 (long independently transcribed non-coding RNA 1180)
Gene: Long non-coding RNA gene on chromosome 17 (44,646,364 to 44,655,076, reverse strand). Ensembl gene ENSG00000266979.
Diseases named in the same sentence as LINC01180 in open-access papers:
LINC01180 is named in the same sentence as 1 disease in open-access papers, as found by Europe PMC text mining. Sharing a sentence is not in itself a finding about the gene and the disease. The quoted sentences say what the papers report.
cancer (1 paper, 2021). A tumor composed of atypical neoplastic, often pleomorphic cells that invade other tissues. "LINC01180 has a role in physiological and pathological processes, including cancer." (PMID 34150649, 2021).